IL1B (interleukin 1 beta)
Diseases named in the same sentence as IL1B in open-access papers (continued):
Sharing a sentence is not in itself a finding about the gene and the disease.
tumor (continued). "IL-1β mainly contributes to the establishment of systemic inflammation in the tumor microenvironment and tumor progression." (PMID 33686176, 2021). "We also assessed the infiltration of CD163+ macrophages in primary tumours overexpressing IL-1B in IL-1Bfl/fl and IL-1B−/− mice." (PMID 34290237, 2021). "Mainly IL-1β and, to a lesser extent, IL-18 have been shown to be involved in tumor proliferation, survival, metastasis, angiogenesis, and immunosuppression, thus promoting the development and progression of cancers." (PMID 34684819, 2021). "Tumor-associated macrophages (TAMs) also secrete IL-1β, which, together with the actions of TNF-α stimulate tumor angiogenesis by inducing the release of VEGF and CXCL8 by HNSCC cells." (PMID 35048046, 2021). "Meanwhile, several immunostimulatory and inflammatory cytokines were brought into play in tumor suppression, including GM‐CSF, IL‐1β, and TNFα." (PMID 33854892, 2021). "Here, we found that tumor necrosis factor α (TNFα) produced by CAR-T cells upon tumor recognition and interleukin 1β (IL1β) secreted by activated myeloid cells were the main cytokines in inducing endothelial activation." (PMID 34093519, 2021). "Amongst the several cytokines tested, a significant increase in IL-1β response to IDPG supplementation was notable due to IL-1β being necessary for inducing a specific adaptive anti-tumor response." (PMID 33898412, 2021). "Next, we investigated IL-1β expression in CRC and non-tumor tissues using TCGA database, which verified dramatic elevation of IL-1β expression in CRC; and consistently, the methylation level of miR-135a-5p was higher in the IL-1βhigh group." (PMID 34667160, 2021). "Several studies have demonstrated that IL1α and IL1β are overexpressed in various tumours including endometrial cancer, and promote cell proliferation, adhesion, invasion, and angiogenesis." (PMID 34357126, 2021). "The antibacterial and anti-tumor immune responses from the M1 macrophages are executed by releasing pro-inflammatory cytokines (such as IL-12, IL-1β, IL-2, IL-6, IL-23, and TNF-α), NO, ROS, and chemokines." (PMID 33883988, 2021). "IL-1β in tumor cells induces epithelial to mesenchymal transition (EMT) and correlates with recurrence and bone relapse in patients with stage II and III breast cancer." (PMID 34745140, 2021). "Confirming this tenet, dectin-1 deficient mice showed diminished IL-1β, reduced infiltration of Tregs and MDSC in the tongues, as well as slower progression and reduced severity of tumor burden." (PMID 33968777, 2021). "Interleukin-1β(IL-1β) is highly expressed in tumor cells and bone marrow cells during progression of bone metastasis." (PMID 34745140, 2021). "In DSS-induced colitis mice treated with miR-19a mimic, colon tumor numbers, sizes and tumor loads are higher compared to the control group; pro-inflammatory cytokines, including IL-1β, IL-6, IL-17a, IFN-γ and TNF-α are also upregulated." (PMID 33921348, 2021). "It is known that Notch signaling regulates many components in the tumor microenvironment, such as the expression of pro-inflammatory cytokines IL1β and CCL2, and plays an important role in effector T cell differentiation." (PMID 33466719, 2021). "Taken together, these data suggest that tumour-derived IL-1B signalling, via IL1R1 activation, inhibits primary tumour growth, while enabling tumour invasion." (PMID 34290237, 2021). "For example, IL1β is required by CD56bright NK cells to produce IFNγ to activate pyroptosis, necessary for the anti-microbial and anti-tumor activity of NK cells." (PMID 34447383, 2021). "In OSCC, IL-1β produced by tumor cells can act in a paracrine manner, inducing the expression of fascine that is associated with ECM degradation and tumor cell invasion." (PMID 35048046, 2021).
tumor (continued). "Furthermore, the administration of tumour-derived IL-1β into tumour-bearing mice was shown to significantly suppress tumour growth by inducing an influx of tumour-associated neutrophils (TANs) to the tumour site, while the decrease of TANs significantly abrogated IL-1β-mediated antitumour activity." (PMID 33918087, 2021). "The bacteria were shown to induce the production of IL‐1β and IL‐23 by myeloid cells, which triggered high proliferation and activation of Vγ6+Vδ1+ tissue‐resident γδ17 T cells that supported tumor growth." (PMID 33188652, 2021). "IL-1β has been shown to facilitate BC tumor metastasis by multiple routes, including modulating the immune cell milieu, promoting the recruitment of MDSCs, and increasing adhesion molecules levels at the metastasis sites." (PMID 34631556, 2021). "In contrast, in lung cancer, prostate cancer, breast cancer, and head and neck squamous cell carcinoma, the NLRP3 inflammasome, IL-1β, and IL-18 promote tumor growth, proliferation, invasion, and metastasis." (PMID 33534121, 2021). "These mice suffered from increased tumour burden and attenuated levels of IL-1β and IL-18, indicating that the inflammasome and its downstream cytokines play a protective role against CAC." (PMID 33918087, 2021). "On the other hand ASC is also recognized as an inflammasome complex adaptor molecule, which mediates inflammatory cytokines production (such as IL-1β and IL-18), mediating tumor-promoting functions." (PMID 34571825, 2021). "IL-10 inhibits tumor growth by hindering several inflammatory and angiogenic factors, including vascular endothelial growth factor, IL-1β, TNF-α, and IL-6." (PMID 34361836, 2021). "On the other hand, activation of IL-1β in the tumor microenvironment can induce shift of macrophages into the M1 subtype, thus contributing to host defense mechanisms and anti-tumor immunity." (PMID 34957538, 2021). "The fluorescence signal of TNF-α and IL-1β in DOX was most evident, consistent with previous studies that DOX chemotherapy can increase the production of TNF-α and IL-1β and promote the proliferation and metastasis of tumor cells." (PMID 34120620, 2021). "Particularly, tumor-infiltrating macrophages expressing IL-1β were found to be the major actor in this pathological condition." (PMID 34696348, 2021). "Macrophages present in the tumour microenvironment (tumour-associated macrophages, TAM), which produce IL-1β." (PMID 33658555, 2021). "It provokes a high production of pro-inflammatory cytokines such as interleukin (IL)-1β and IL-18 in response to the danger signals in tumour microenvironment (TME), resulting in the activation of a pro-inflammatory immune response." (PMID 33918087, 2021). "For assessing the significant correlation of KLF4 and IL-1β with tumor purity and tumor-infiltrating functional immune cells in LUAD and LUSC, TIMER database was queried." (PMID 34440860, 2021). "Our findings indicate significant upregulation of the examined interleukins (IL-1β, IL-6 and IL-17) in the surgical margin in comparison to the tumour lesion." (PMID 33658555, 2021). "Activated GSDMD/GSDME protein leads to the formation of membrane pores and mediates the maturation and release of IL-1β and IL-18, which subsequently induces strong inflammatory response in tumor microenvironment." (PMID 34830775, 2021). "IL-1β represents a cytokine involved in the pathophysiology of cancer, with direct targeting a viable avenue to treat cancer cachexia as well as tumour load per se." (PMID 33907915, 2021). "A dual role for IL-1β in carcinogenesis, tumor growth, invasion, and metastasis has also been suggested." (PMID 35048001, 2021). "Indeed, pivotal pro-inflammatory cytokines, including tumor necrosis factor-α (TNF-α) and interleukin-1β (IL-1β), may be secreted by tumor-associated macrophages to further promote tumor cell growth, migration, invasion, and the epithelial to mesenchymal transition, mainly via the NF-κB pathway." (PMID 34046348, 2021).
tumor (continued). "Cells that constitute the tumor stroma provide many factors to initiate and/or support tumorigenesis, including the pro-inflammatory cytokines IL-1β and TNF-α." (PMID 34046348, 2021). "IL-1β can increase tumor invasion and metastasis mainly by promoting angiogenic factors produced by stromal cells in the TME to induce tumor angiogenesis, endothelial cell activation, and immunosuppressive cells." (PMID 34079469, 2021). "We assessed the infiltration of CD8+ T cells in primary tumours from wild-type and IL-1B overexpressing E0771 tumour cells in IL-1Bfl/fl and IL-1B−/− microenvironments." (PMID 34290237, 2021). "We included both anti- and pro-inflammatory cytokines involved in tumor suppression such as TNF-α, IL-1β, and tumor promotion such as IL-10, CCL22, CXCL5, and TGF-β (selection of cytokines based on ref.)." (PMID 33267818, 2020). "On the other hand, tumour cells produce TNF-α and IL-1β, which activate pro-angiogenic growth factors to cause enhanced tumour growth." (PMID 32512860, 2020). "Downstream of RLR family members, expression of NLRP3 inflammasome components are impaired in HCC tumor tissues, i.e., ASC, caspase 1 and IL-1β, which inversely correlated with tumor grade and clinical stage." (PMID 33613561, 2020). "These tumor-associated macrophages (TAMs) release a wide variety of cytokines including TNF-α and IL-1β to activate NF-κB in cancer cells and promote Snail1 expression, inflammation, cancer stem cell niches, and all aspects of tumor progression." (PMID 31936290, 2020). "Of note, we found increased levels of several immunosuppressive cytokines such as Tslp, transforming growth factor β (Tgfβ), Il10, and Inos as well as of pro‐inflammatory cytokines such as Tnfα, Il1β, Ifnγ, and Il17 in tumor lesions compared to control skin." (PMID 32615027, 2020). "Although there was a slight difference in the IL-6 and TNF-α mRNA levels, the IL-1β cytokine levels were elevated in tumours injected with IL-33." (PMID 33308251, 2020). "In contrast to the presence of infiltrating F4/80-positive macrophages and the elevated expression of F4/80 and Ly6c, the mRNA expression of TNFα, IL-6, Il-1β, and IL-17 were paradoxically downregulated in the tumor-bearing 12-month-old Atg7ΔHep livers." (PMID 32382012, 2020). "Inflammasome complexes are expressed in various tumors or cancer cells and regulate tumor development by maturing and secreting IL-1β into the tumor microenvironment." (PMID 32397236, 2020). "Classical activation of M1 macrophages in response to IFN-γ is characterized by a high ability to express antigens, high expressions of iNOS, IL-6, TNF-α, IL-1β mRNA, and nitric oxide (NO), which can kill endogenous pathogens and tumor cells." (PMID 33240950, 2020). "Similar to what occurred in KPC‐conditioned media treated primary microglia, we observed increased expression of Il‐1b and Arg1 in the hypothalami of tumor‐bearing animals compared to sham animals, whereas there was decreased expression of Nos2 and Tmem119." (PMID 32039522, 2020). "In support of this mechanism in response to tumour initiation, in vitro studies have shown that IL-1β, TNFα and IL-6 expression are induced by transformation with oncogenic forms of Ras in various human and mouse cell types." (PMID 32325966, 2020). "The mRNA expression of different pro-tumor factors such as interleukin-1β (IL-1β), CC-chemokine ligand-2-4 (CCL2, CCL3, CCL4), Interleukin-23 (IL-23) and inducible nitric oxide synthase (iNOS), was analyzed." (PMID 33049964, 2020). "Silencing of ID1 significantly abrogated the tumor sphere formation induced by IL-1β stimulation (P < 0.05, vs. all other groups)." (PMID 32547321, 2020). "We tested the effect of inflammatory cytokines commonly found in tumor microenvironment including IL-1β, IL-6, IL-10, TNF-α, and IFN-γ on TDO2 expression on MUM cells." (PMID 32050636, 2020). "MC-derived TNF-α possesses tumor-suppressive activity while IL-1β supports tumor progression and metastasis." (PMID 32086776, 2020).
tumor (continued). "Microbiota‐induced or IL‐1β‐induced overexpression of MMPs is a crucial factor in tumor migration, as degradation of extracellular matrix and loss of cell‐cell or cell‐matrix adhesion caused by MMPs might contribute considerably to tumor invasion and tumor spread." (PMID 32638533, 2020). "We treated GBM cells and PBMCs with IL-1β and found dramatically increased expression levels of the proinflammatory and tumor-promoting mediators COX2, IL-1β, CCL2, and IL-8 in both GBM cells and PBMCs." (PMID 32069807, 2020). "IL-1β has been reported to be the factor that makes the tissue environment favorable for solid tumor progression through the acceleration of tumor cell growth, invasion, and neovascularization." (PMID 33362799, 2020). "ICAF formation can be triggered by the TLR4-mediated induction of IL-1β in tumor cells, which promotes the transdifferentiation of CAFs into iCAFs." (PMID 33022971, 2020). "Conditionally inactivated NF-κB in myeloid cells significantly reduced the expression of many inflammation-related genes, such as IL-1β, TNFα, human macrophage inflammatory protein, and cyclooxgenase 2, and tumor size significantly decreased in mice." (PMID 32317968, 2020). "IL1β was expressed predominantly in clusters of cells that resembled migrating immune cells throughout the stroma of tumor ovaries." (PMID 31923221, 2020). "IL-1β is the most important member of the IL-1 family, with strong inflammatory activity and related to regulation of tumor microenvironment and tumor progression." (PMID 32358484, 2020). "Consistent with the in vitro data, these tumor-infiltrating macrophages also showed increased ROS levels, enhanced caspase-1 activity and elevated mature IL-1β production following L-MP treatment." (PMID 31649305, 2020). "P2X7 systemic blockade activated an ICD–like mechanism in cancer cells leading to tumor growth reduction and activation of antitumor responses while reducing the tumor-promoting inflammatory cytokine IL-1β." (PMID 32581786, 2020). "The upregulation was accompanied by upregulation of distinct cytokines with the most prominent being Tnfα and Ifnβ in tumor cells and Ifnβ and Il1β in macrophages." (PMID 33202881, 2020). "We have seen that IL-1β is generally a promoter of cancer by acting on cancer cell proliferation and invasion, neo-angiogenesis, or tumor infiltrating immune cells." (PMID 32635472, 2020). "More importantly, tyrosine kinase inhibitor treatment-induced L-MPs also induce human macrophages to release IL-1β, leading to a tumor-promoting effect in a humanized mouse model." (PMID 31649305, 2020). "With the stimulation of IL-1β, B16-F10 tumor cells formed larger size of tumors than untreated tumor cells (P = 0.046)." (PMID 32547321, 2020). "In the 4T1 murine model, which is used as a preclinical model for invasive breast cancer, IL-1β promotes tumor growth and the capacity of cells to metastasize." (PMID 33042810, 2020). "It has already been demonstrated that prolonged treatment with IL-1β at the concentrations of 0.1, 1 or 10 ng/mL induces cell death in tumor cells." (PMID 33322510, 2020). "Cytokines such as Interleukin 6 (IL-6), Tumor Necrosis Factor alpha (TNF-α), Interleukin- 1β (IL-1β) and Interleukin 10 (IL-10), which are released peripherally and in the tumor microenvironment, can act locally in reciprocal signaling interactions." (PMID 33126617, 2020). "Consistent with this, in our immunohistochemical staining experiments, caspase-1 and IL-1β in RCC cancer tissues were stained more lightly than in non-tumor tissues." (PMID 32303673, 2020). "* Myeloid cells were connected to tumor recurrence following surgery and to exitfrom dormancy.* Myeloid cells acted in this respect via soluble mediators like TNFα, IL-1β and VEGF-A,and through COX enzymes." (PMID 33585241, 2020). "The presence of IL-1β in the tumor microenvironment is correlated with the greater occurrence of metastases, cell proliferation and angiogenesis." (PMID 33126617, 2020).
tumor (continued). "STAT3 pathways are activated by some of these cytokines, and their activation of malignant cells stimulates their proliferation and survival; indeed, upregulating cytokines IL-1β and IL-6 promotes angiogenesis and tumor invasion." (PMID 32156252, 2020). "In contrast to IL-1β and IL-4, IL-10 overexpression elicits tumor rejection by stimulating cytotoxicity of CD8 (+) T cells by inducing the expression of IFN-γ in CD8 (+) T cells." (PMID 33112542, 2020). "In the primary lesion of cancer cells, NLRP3 drives the production of pro-IL-1β, DC maturation, and the secretion of IL-1β to support the differentiation of tumor-specific CD8+ T cells." (PMID 33613533, 2020). "Previous study has showed that VEGF, TNF-α, IL-1β and MMPs derived from TAMs involve in tumor angiogenesis." (PMID 33201893, 2020). "We demonstrate that cancer-specific bcl-2 promotes an IL-1β-driven pathway supporting the recruitment of M2 polarized macrophages, as well as formation of a pro-tumor microenvironment." (PMID 32269145, 2020). "The establishment of this immunosuppressive tumor microenvironment by IL-1β can be explained by the fact that tumor-derived IL-1β activates pancreatic stellate cells (PSCs), which in turn shape CAFs." (PMID 33261061, 2020). "Secreted IL-1β and IL-2 can enhance the differentiation of Th9 cells, and TNF will cause tumor cells to die." (PMID 32228589, 2020). "Meanwhile, tumor-derived granulocyte-macrophage colony-stimulating factor, IL-1β, VEGF, and PGE2 lead to the accumulation of MDSCs in the tumor microenvironment." (PMID 32983126, 2020). "The importance and influence of IL-1B in tumor development and tumor immunity have been conclusively demonstrated for various diseases." (PMID 32527212, 2020). "The local expression of IL-1β in tumor sites has been correlated with increased invasiveness in experimental tumors and in cancer patients and is associated with a bad prognosis." (PMID 33322216, 2020). "Zebrafish skin and liver cancer models showed an upregulation of the pro-inflammatory cytokines IL-1β and TNFα in response to tumour initiation." (PMID 32325966, 2020). "The present study showed that DHA, an anti-malarial drug, significantly reduced IL-1β production in the xenograft tumor microenvironment of Hep-2 cells in nude mice." (PMID 32577124, 2020). "Similar to IL-1β, IL-18 production and secretion were increased in all tumor cell lines treated with LPS/Nigericin compared to untreated control." (PMID 33613529, 2020). "Delivery of an anti-IL-1β neutralizing antibody also reduces the antitumor properties of other anthracycline chemotherapy in established tumor models." (PMID 33584721, 2020). "Sonic hedgehog-activated stromal cells in the tumor microenvironment also secrete several immune mediators including interleukin (IL)-6 and IL-1β which in turn recruit myeloid-derived suppressor cells (MDSCs) to the tumor microenvironment." (PMID 35582227, 2020). "Another significant effect of IL-1β promoting tumor metastasis is its ability to potentiate tumor angiogenesis." (PMID 33322216, 2020). "Within a tumor, IL-1β is produced and secreted by various cell types, such as immune cells, fibroblasts, or cancer cells." (PMID 32635472, 2020). "In the same study, an increase in inflammatory markers such as IL-1β, IL-6, iNOS, and TNFα was also observed in the tumor of voluntary runners." (PMID 33613297, 2020). "In fact, chemotherapy and radiation can trigger the production of IL-1β by either cancer cells or tumor infiltrating cells, such as macrophages, DCs, or MDSCs." (PMID 32635472, 2020). "The crucial crosslink between inflammasomes and immune-related diseases is the activation of IL-1β; immune stromal and tumor cells can produce IL-1β, which also stimulates the expression of cyclooxygenase (COX)-2, IL-6 and chemokine C-C motif ligand (CCL)." (PMID 32796686, 2020).